CHAMP1 (chromosome alignment maintaining phosphoprotein 1)
Description:
Required for proper alignment of chromosomes at metaphase and their accurate segregation during mitosis. Involved in the maintenance of spindle microtubules attachment to the kinetochore during sister chromatid biorientation. May recruit CENPE and CENPF to the kinetochore.
Synonyms: C13orf8; CAMP; CHAMP; ZNF828; MRD40; NEDHILD
Tractability: Small molecule: a structure with a bound ligand is known. PROTAC: UniProt records ubiquitination sites on it; ubiquitination databases record sites on it; its protein half-life has been measured.
Gene: Protein-coding gene on chromosome 13 (114,314,482 to 114,337,626, forward strand). Ensembl gene ENSG00000198824.
Subcellular location: Nucleus; Chromosome; Chromosome, centromere, kinetochore; Cytoplasm, cytoskeleton, spindle
Subcellular location (Human Protein Atlas): Nucleoplasm; Nuclear bodies
Gene Ontology:
Molecular function: protein binding
Biological process: attachment of mitotic spindle microtubules to kinetochore; protein localization to kinetochore; protein localization to microtubule; sister chromatid biorientation
Cellular component: condensed chromosome; kinetochore; nuclear body; nucleoplasm; nucleus; spindle; chromosome
Genetic constraint (gnomAD): Loss-of-function variants: 4 observed, 57.07 expected, observed/expected ratio (o/e) 0.0701, 90% interval 0.034 to 0.16. The upper end of that interval is the gene's LOEUF score, 0.16, which puts it in group 1 of 6, group 1 being the genes least tolerant of losing a copy. Missense variants: 994 observed, 1,021.7 expected, observed/expected ratio (o/e) 0.97, 90% interval 0.92 to 1.02. Synonymous variants: 368 observed, 361.69 expected, observed/expected ratio (o/e) 1.02, 90% interval 0.93 to 1.11.
Gene-disease validity (ClinGen):
ClinGen rates the evidence that CHAMP1 causes each of these diseases.
complex neurodevelopmental disorder (autosomal dominant): Definitive. A disorder that involves more than one phenotype associated with the central nervous system, including but not limited to intellectual disability, autism, and seizures (epilepsy).
Homologues: Orthologues: macaque CHAMP1 (98% identical), dog CHAMP1 (92% identical), rabbit CHAMP1 (90% identical), chimpanzee CHAMP1 (84% identical), rat Champ1 (77% identical), mouse Champ1 (76% identical).
Diseases named in the same sentence as CHAMP1 in open-access papers:
CHAMP1 is named in the same sentence as 17 diseases in open-access papers, as found by Europe PMC text mining. Sharing a sentence is not in itself a finding about the gene and the disease. The quoted sentences say what the papers report.
developmental delay (4 papers, 2021 to 2024). "Our results provide evidence that individuals with CHAMP1 mutations are more affected than those with deletions of CHAMP1, although both display clinically significant developmental delays and adaptive impairments." (PMID 37454340, 2023). "CHAMP1-related neurodevelopmental disorder, or CHAMP1 disorder, is a recently described genetic syndrome associated with developmental delay, intellectual disability, behavioral symptoms, medical comorbidities, and dysmorphic features." (PMID 35271727, 2022). "CHAMP1 mutation should be considered when a patient presents with global developmental delay and microcephaly." (PMID 34404773, 2021).
Intellectual disability (4 papers, 2021 to 2024). "CHAMP1 is a gene associated with intellectual disability, which was originally identified as being involved in the maintenance of kinetochore–microtubule attachment." (PMID 36106092, 2022). "The clinical presentation of CHAMP1 mutation includes intellectual disability (17/17), motor development delay (14/17), facial dysmorphism (10/12), eye anomalies (14/16), and microcephaly (12/17)." (PMID 34404773, 2021).
Obesity (2 papers, 2018 to 2023). Accumulation of substantial excess body fat. "Chromosome 13q34 deletions disrupting the CHAMP1 gene were linked ID, obesity and mild dysmorphism in five adult individuals." (PMID 29441128, 2018). "Subsequently, there have been reports of cases involving obesity and one case report of hyperinsulinemia in patients with CHAMP1 mutations, thus suggesting the possible presence of an underlying metabolic syndrome in CHAMP1 patients that was not highlighted till date." (PMID 37628598, 2023).
Anxiety (1 paper, 2022). Intense feelings of nervousness, tension, or panic often arise in response to interpersonal stresses. "Interestingly, anxiety and depression were frequently manifested in individuals with CHAMP1 mutations, suggesting that depression-like behaviour is a characteristic phenotype of CHAMP1 deficiency." (PMID 36106092, 2022).
depression (1 paper, 2022). "CHAMP1 deficiency delayed neuronal development and CHAMP1 heterozygous knockout mice exhibited mild memory defects, altered social interaction, and depression-like behaviours, resembling some aspects of the human phenotype." (PMID 36106092, 2022). "In a behavioural test battery, adult CHAMP1 heterozygous knockout mice showed mild memory defects, altered social interaction, and depression-like behaviours." (PMID 36106092, 2022). "In a behavioural test battery, CHAMP1+/− mice exhibited mild memory defects, altered social interaction, and depression-like behaviours." (PMID 36106092, 2022). "In a behavioural test battery, CHAMP1 heterozygous knockout mice exhibited mild memory defects, altered social interaction and depression-like behaviours." (PMID 36106092, 2022).
gastroesophageal reflux (1 paper, 2021). "A de novo novel pathogenic nonsense variant [p.(Lys620*)] in CHAMP1 was identified in the DNA sample obtained from FIN20-3, which presented with moderate to severe ID, strabismus, constipation, gastroesophageal reflux (GER) and frontal hypoplasia." (PMID 33710394, 2021).
metabolic syndrome (1 paper, 2023). A cluster of metabolic risk factors for CARDIOVASCULAR DISEASES and TYPE 2 DIABETES MELLITUS. "Nevertheless, investigating the presence of any metabolic syndrome in cases with CHAMP1 mutations is needed for a better follow-up and clinical management of this population." (PMID 37628598, 2023).
neurodevelopmental disorder (2 papers, 2023). A behavioral and cognitive disorder with onset during the developmental period that involves impaired or aberrant development of intellectual, motor, or social functions. "CHAMP1, or chromosome alignment maintaining phosphoprotein 1, is a gene located on the long arm of chromosome 13 and mutations in the gene are associated with CHAMP1-related neurodevelopmental disorder, or CHAMP1 disorder." (PMID 37454340, 2023). "CHAMP1 is associated with a dominant neurodevelopmental disorder with dysmorphic features." (PMID 37234784, 2023).
CHAMP1 also shares sentences with these, for which no sentence is quoted: microcephaly (2 papers); tumor (2); autism (1); breast carcinoma (1); cancer (1); Hyperinsulinemia (1); lung carcinoma (1); Strabismus (1); white-sutton syndrome (1).